ENSG00000287005 (novel transcript, antisense to XXYLT1)
Synonyms: LOC124909475
Gene: Long non-coding RNA gene on chromosome 3 (195,260,632 to 195,263,628, forward strand). Ensembl gene ENSG00000287005.
Gene Ontology:
Biological process: SRP-dependent cotranslational protein targeting to membrane, signal sequence recognition
Cellular component: signal recognition particle, endoplasmic reticulum targeting